RNY4P16 (RNY4 pseudogene 16)
Gene: Miscellaneous RNA gene on chromosome 1 (234,837,976 to 234,838,069, forward strand). Ensembl gene ENSG00000201638.
Homologues: Orthologues: chimpanzee Y_RNA (99% identical). Paralogues in human: RNY4 (85% identical), RNY4P6 (83% identical), RNY4P10 (82% identical), RNY4P25 (82% identical), Y_RNA (82% identical), RNY4P13 (81% identical), RNY4P19 (81% identical), RNY4P23 (81% identical), RNY4P7 (81% identical), RNY4P9 (81% identical), Y_RNA (81% identical), RNY4P14 (80% identical), and 83 more.